LRRK2 (leucine rich repeat kinase 2)
Diseases named in the same sentence as LRRK2 in open-access papers (continued):
Sharing a sentence is not in itself a finding about the gene and the disease.
autism (4 papers, 2020 to 2026). Persistent deficits in social interaction and communication and interaction as well as a markedly restricted repertoire of activity and interest as well as repetitive patterns of behavior. "On one hand, comparative genomic mapping with microdeletions has suggested that deletion of LRRK2 can cause a syndrome that presents as intellectual disability and autism." (PMID 40371391, 2025). "In parallel with decreased striatal dopaminergic neurite density, LRRK2 G2019S neurons show increased autism-linked CNTN5 adhesion protein expression; glial cells show significant loss of ferritin heavy chain." (PMID 38293195, 2024). "In contrast to the gain-of-function mechanism involved in LRRK2-mediated autosomal-dominant PD, intellectual disability or autism appears to be due to LRRK2 loss-of-function from haploinsufficiency." (PMID 31963867, 2020). "One possible reason for this discrepancy is that autism may occur as a result of a genetic interaction between LRRK2(LOF) and variants in other neurodevelopmental genes." (PMID 40371391, 2025). "In contrast, late-diagnosed autism reflects a "Failure to Refine," arising from astrocyte dysfunction, complement-mediated over-pruning, and LRRK2 dysregulation during adolescent circuit remodelling, with strong transcriptomic convergence to ADHD." (PMID 42006518, 2026). "Patient DGDP289A displays developmental delays, autism, impaired motor skills and craniofacial anomalies and has a ~328 kb minimal microdeletion at 12q12, encompassing LRRK2 and MUC19." (PMID 31963867, 2020). "The high level of LRRK2 expression in the different regions of the brain, particularly in the hippocampus, is consistent with a potential role in autism and learning disability." (PMID 31963867, 2020). "The neurological function of LRRK2, along with the results of comparative deletion mapping, suggest that this gene is likely to be involved in intellectual disability, craniofacial anomalies, and autism." (PMID 31963867, 2020). "Moreover, we have discussed genetic interactions suggesting that the LRK-1 ortholog of LRRK2 regulates axon development by functioning in a pathway with the ortholog of the WDFY3 selective autophagy protein (aka Alfy), which is encoded by an autism-associated gene." (PMID 40371391, 2025). "However, it may prove restorative in post-pubertal individuals with late-diagnosed autism and ADHD comorbidity by counteracting astrocyte dysfunction, excessive complement tagging, and LRRK2-related pruning dysregulation." (PMID 42006518, 2026).
colon carcinoma (4 papers, 2014 to 2025). "Despite these revelations, the underlying mechanisms of LRRK2 G2019S-mediated tumorigenesis remain largely elusive, necessitating empirical scrutiny into its role in colon cancer development." (PMID 38607004, 2024). "Our data suggest that the LRRK2 G2019S mutation enhances the production of IL-1β, IL-6 and IL-11 in the colon tumor microenvironment, thereby activating the NF-κB and STAT3 signaling pathways." (PMID 38607004, 2024). "In this study, employing a colitis-associated cancer (CAC) model and LRRK2 G2019S knock-in (KI) mouse model, we demonstrate that LRRK2 G2019S promotes the pathogenesis of colon cancer, characterized by increased tumor number and size in KI mice." (PMID 38607004, 2024). "Despite this observation, the underlying mechanisms linking LRRK2 G2019S to colon cancer remain elusive." (PMID 38607004, 2024). "Targeting LRRK2 kinase activity may emerge as a novel therapeutic strategy for colon cancer patients, particularly those harboring the G2019S mutation." (PMID 38607004, 2024). "In summary, the current study suggests that LRRK2 G2019S promotes colon cancer through LRRK2–GSDMD signaling axis-mediated intestinal inflammation." (PMID 38607004, 2024). "Recent studies have further suggested that LRRK2 G2019S PD patients exhibit drastically increased risks of colon cancer and leukemia compared with idiopathic PD patients." (PMID 38607004, 2024). "Taken together, our findings offer experimental evidence indicating that the gain-of-kinase activity in LRRK2 promotes colorectal tumorigenesis, suggesting LRRK2 as a potential therapeutic target in colon cancer patients exhibiting hyper LRRK2 kinase activity." (PMID 38607004, 2024). "After AOM/DSS induction, both LRRK2 KI mice and WT controls developed colon tumors and the tumors were exclusively clustered in the distal colon." (PMID 38607004, 2024). "Consequently, we observed elevated phosphorylation levels of STAT3 and p65 in LRRK2 G2019S colon tumors, accompanied by upregulation of downstream molecules such as Bcl-xL, cyclin D1 and COX-2." (PMID 38607004, 2024). "Consistent with this, LRRK2 G2019S mice did not develop colon tumors when subjected to a single AOM injection or repeated DSS treatment alone 65 days after treatment." (PMID 38607004, 2024).
motor neuron disease (4 papers, 2008 to 2022). "Kinase activating missense mutations in LRRK2 represent the largest known cause of Parkinson’s disease (PD) with corticobasal degeneration and associated motor neuron disease in some patients." (PMID 36614124, 2022).
retinal degeneration (4 papers, 2014 to 2025). Degeneration of the retina. "Remarkably, CFAP20 interacts with disease-causing proteins including: (i) ARL2BP, associated with RP, (ii) TBC1D32 and FOXJ1, related with ciliopathies, and (iii) LRRK2 and DICER1, involved in retinal degeneration in animal models." (PMID 35246562, 2022).
triple-negative breast carcinoma (4 papers, 2020 to 2022). An invasive breast carcinoma which is negative for expression of estrogen receptor (ER), progesterone receptor (PR), and human epidermal growth factor receptor 2 (HER2). "In triple-negative breast cancer, long intergenic non-coding RNA for kinase activation (LINK-A) mediates hypoxia inducible factor 1 subunit alpha (HIF1α) phosphorylation and stabilization by protein tyrosine kinase 6 (BRK) and leucine rich repeat kinase 2 (LRRK2) interaction." (PMID 32429086, 2020).
viral infections (4 papers, 2014 to 2025). "The differential effect of HPgV infection on these pathways between WT and LRRK2 genotypes highlights a potentially novel mechanism by which viral infections interact with genetic risk factors to modulate neurodegenerative processes in PD." (PMID 40626361, 2025). "SPOCK2 expression was shown to be associated with lung injury induced by viral infection and the mouse LRRK2 knockout model suggested that LRRK2 regulates innate immune responses and lung inflammation during Mtb infection." (PMID 37471455, 2023). "As such, we sought to investigate the contribution of these genes in a CNS-targeted, viral infection model, minimizing peripheral immune system involvement; to this end, we measured Lrrk2- and Snca-dependent outcomes following a direct-brain inoculation of murine pups with reovirus T3D." (PMID 40471880, 2025).
Cerebral ischemia (3 papers, 2018 to 2021). Restriction of arterial blood supply to the brain associated with insufficient oxygenation to support the metabolic requirements of the tissue. "George T and his colleagues reported that LRRK2 may result in neuronal apoptosis after cerebral ischemia by modulating the phosphorylation of Tau48." (PMID 34848837, 2021). "It has been reported that LRRK2 could be promoting post-ischemic apoptotic cell death by modulating Tau phosphorylation in experimental cerebral ischemia." (PMID 30645642, 2019). "In addition to its toxic effects in PD, LRRK2 also promotes post-ischemic apoptotic cell death by modulating Tau phosphorylation in experimental cerebral ischemia." (PMID 29545743, 2018). "Notably, LRRK2 may contribute to neuronal apoptosis following cerebral ischemia by modulating the phosphorylation of Tau, a microtubule-associated protein that is predominantly expressed in the CNS and that regulates neurite outgrowth and axonal transport." (PMID 29545743, 2018).
COVID-19 (3 papers, 2022 to 2023). A disease caused by infection with severe acute respiratory syndrome coronavirus 2. "In addition, some mito-DEGs were reversely altered in the AT2 and AT1 subsets (e.g., LRRK2, PID1, SOD2, CLIC4, and ERBB4) or showed altered expression in the AT2 or AT1 subset in patients with COVID-19 (–D)." (PMID 35844544, 2022).
developmental delay (3 papers, 2013 to 2020). "Collectively these data support the idea that LRRK2 can regulate patterns of neurite growth–a finding that may translate into a developmental delay or modest alterations in connectivity." (PMID 23646112, 2013). "This would be consistent with the absence of overt morphological differences that have been reported in a variety of brain areas in adult LRRK2 mouse models, but a developmental delay may be relevant to PD as it could impart vulnerability consistent with the adult onset of PD." (PMID 23646112, 2013).
encephalitis (3 papers, 2020 to 2025). An acute inflammatory process affecting the brain parenchyma. "The Lrrk2 p.G2019S variant was examined for its impact on acute outcomes in reovirus T3D-induced encephalitis following intracerebral inoculation." (PMID 40471880, 2025). "In line with the reported protective effects against intestinal infections, mouse pups carrying the LRRK2 G2019S mutation displayed reduced viral titers during reovirus (serotype 3TD)-induced encephalitis." (PMID 32410948, 2020). "Curiously, mutant LRRK2 induced an enhanced proinflammatory state that was protective during sepsis, but proved to be detrimental during encephalitis as it was linked to a higher mortality rate." (PMID 32410948, 2020). "Here, we examined whether outcomes of direct inoculation of the brain by reovirus T3D, which invariably causes lethal encephalitis within 15 days, would also be modified by variants in Lrrk2 and Snca." (PMID 40471880, 2025). "Together, these findings suggest that while variants in the PD-linked Lrrk2 and Snca genes influenced disease outcomes of intranasally acquired reovirus T3D encephalitis, they did not affect survival outcomes in the intracerebrally acquired reovirus T3D encephalitis model." (PMID 40471880, 2025). "Future work will seek to identify the host factors and/or responses that are activated by intranasal infection to modify the severity of subsequent encephalitis in a Lrrk2- and Snca-dependent manner, respectively." (PMID 40471880, 2025). "The primary goal of our study was to determine whether Lrrk2 and α-synuclein function within the brain to protect mice from acute reovirus T3D-induced encephalitis." (PMID 40471880, 2025). "Akin to Lrrk2, and building on our previous discovery that Snca expression was protective against intranasal inoculation of pups with reovirus T3D, we further investigated the antiviral properties of α-synuclein to protect against virus-induced encephalitis." (PMID 40471880, 2025). "Collectively, these findings suggested that neither p.D1994S nor p.G2019S allelic variants in Lrrk2 influenced the course of encephalitis after direct injection of reovirus T3D into the brain." (PMID 40471880, 2025). "In this current study, we sought to determine whether Lrrk2 and α-synuclein also contribute to the immediate antiviral host response as relates to survival outcomes from encephalitis following direct inoculation of the brain." (PMID 40471880, 2025).
epilepsy (3 papers, 2017 to 2025). A brain disorder characterized by episodes of abnormally increased neuronal discharge resulting in transient episodes of sensory or motor neurological dysfunction, or psychic dysfunction. "While direct links between LRRK2 mutations and epilepsy are still under investigation, the gene’s role in neuronal signaling and inflammation suggests a possible connection to seizure susceptibility." (PMID 40283547, 2025). "Research suggests that mutations in genes such as LRRK2 and alpha-synuclein (SNCA) are implicated in both PD and epilepsy." (PMID 40283547, 2025). "For example, we have previously shown that levetiracetam (LEV), a compound widely used in human epilepsy treatment, is able to significantly rescue the pathological effect of LRRK2 in several high-eukaryote cell line models." (PMID 39062128, 2024). "We have previously shown that levetiracetam (LEV), a drug widely used in humans for the treatment of epilepsy, is able to significantly rescue the pathological effect of LRRK2 in cell lines." (PMID 39062128, 2024). "As mentioned in the Introduction, we have previously demonstrated that LEV, a compound widely used in human epilepsy treatment, is able to significantly reduce the LRRK2 pathological effect in highly eukaryotic cell lines." (PMID 39062128, 2024). "In addition, we have shown that levetiracetam—a drug widely used in human epilepsy treatment—is able to reduce neuroinflammation, motor deficits, and neurodegeneration in LRRK2 Drosophila models." (PMID 39062128, 2024). "The published genetic overlap, whether in variants of PRKN, LRRK2, or GABA, is not extensive enough compared to cases with distinct genetic causes of epilepsy or PD." (PMID 40283547, 2025).
gastric cancer (3 papers, 2021 to 2022). A primary or metastatic malignant neoplasm involving the stomach. "GLI3, LAMA1, and LRRK2 are found to be significantly associated with the survival of gastric cancer in subtype C1." (PMID 34728653, 2021). "LRRK2-G2019S carriers have an increased cancer risk, in particular for brain, breast, colon and blood cancers and female gender was associated with a reduced risk of bladder colon, hematological, kidney, liver, lung, rectal, and stomach cancer." (PMID 35247252, 2022).
Gaucher disease (3 papers, 2023 to 2025). Gaucher disease (GD) is a lysosomal storage disorder encompassing three main forms (types 1, 2 and 3), a fetal form and a variant with cardiac involvement (Gaucher disease - ophthalmoplegia - cardiovascular calcification or Gaucher-like disease). "The existing literature on this topic is sparse; most reports addressing LRRK2 are limited in scope, while studies of GBA1 have largely concentrated on patients with Gaucher disease rather than PD cohorts carrying heterozygous pathogenic variants." (PMID 41300754, 2025).
insomnia (3 papers, 2015 to 2023). A sleep disorder characterized by difficulty in falling asleep and/or remaining asleep. "While no previous studies to our knowledge have examined sleep fragmentation in G2019S mice, sleep fragmentation and insomnia have been identified in other animal models of PD, and are reported in patients with idiopathic and LRRK2 PD." (PMID 32477237, 2020). "Sleep complaints are frequent in LRRK2-PDand show a pattern that when compared to IPD is characterized by more frequent sleep onset insomnia, similar EDS and less prominent RBD." (PMID 26177462, 2015). "Sleep complaints were frequent in LRRK2-PD patients; 78% reported poor sleep quality, 33% sleep onset insomnia, 56% sleep fragmentation and 39% early awakening." (PMID 26177462, 2015). "Sleep onset insomnia was more frequent, EDS was similar and RBD was less frequent and severe in LRRK2-PD than in IPD." (PMID 26177462, 2015).
Intellectual disability (3 papers, 2020 to 2025). "Previous studies have shown that alterations in dendrites and dendritic spines are a hallmark of intellectual disability, and the mutations of LRRK2 has been shown to alter dendritic morphology." (PMID 31963867, 2020). "Interestingly, variants of LRRK2 were also associated to cognitive development leading to intellectual disability and ASD." (PMID 35368691, 2022). "The decreased expression of LRRK2 may affect protein–protein interactions between LRRK2 and its binding partners, of which eight have previously been linked to intellectual disability." (PMID 31963867, 2020). "Based on these associations, and the interaction between LRRK2 and known intellectual disability genes, it appears that LRRK2 may play a role in a core molecular pathway that governs cognitive development, though future studies are necessary." (PMID 31963867, 2020). "Thus, the increase in LRRK2 mRNA expression during rodent development appears to coincide with increasing synaptic density and neuronal complexity, making it a likely candidate for intellectual disability, where there are known alterations in dendritic spines and neurite length." (PMID 31963867, 2020).
intracerebral hemorrhage (3 papers, 2019 to 2021). A cerebrovascular disorder characterized by bleeding into one or both cerebral hemispheres including the basal ganglia and the cerebral cortex. "Corroborating these results, LRRK2 induced inflammation, with concomitant dysregulation of the p38 MAPK/Drosha pathway, was induced upon intracerebral hemorrhage in rats." (PMID 30645642, 2019). "Furthermore, our research provided novel insights into the NLRC4 inflammasome after intracerebral hemorrhage and suggested the role of RGS2 in NLRC4 inflammasome activation by LRRK2 after ICH." (PMID 34848837, 2021).
lung adenocarcinoma (3 papers, 2021 to 2024). A carcinoma that arises from the lung and is characterized by the presence of malignant glandular epithelial cells. "While the decrease in the expression of LRRK2 has been reported to cause lung adenocarcinoma (LUAD)." (PMID 36590916, 2022).
Renal atrophy (3 papers, 2016 to 2025). Atrophy of the kidney. "Consistent with previous studies, LRRK2R1627P and LRRK2-/- rats exhibited age-dependent renal atrophy." (PMID 39500355, 2024). "Interestingly, these LRRK2−/− mice exhibit age-dependent renal atrophy, increased α-synuclein aggregation, impaired autophagy-lysosome pathway, and increased apoptosis and inflammation in kidneys." (PMID 27872856, 2016).
Salmonella Infections (3 papers, 2021 to 2025). Infections with bacteria of the genus SALMONELLA. "Also, inhibition of LRRK2 kinase by GSK2578215A enhances the susceptibility of mice to Salmonella infection." (PMID 40867920, 2025). "Noteworthy is also the activation of the NLRC4 inflammasome by active LRRK2 during Salmonella infection." (PMID 33426511, 2021). "Further, it would be interesting to determine whether PPM1H is up-regulated in response to Salmonella infection to counteract the protective role of the LRRK2-Rab32-IRG1 complex." (PMID 39874296, 2025).
Sleep disturbance (3 papers, 2008 to 2025). An abnormal pattern in the quality, quantity, or characteristics of sleep. "Furthermore, as LRRK2 mutation carriers are known to be associated with sleep dysfunction, they may not be good candidates for CASI." (PMID 35754954, 2022).
acute kidney injury (2 papers, 2012 to 2025). Sudden and sustained deterioration of the kidney function characterized by decreased glomerular filtration rate, increased serum creatinine or oliguria. "LRRK2, a kinase involved in mitochondrial homeostasis, and has been shown to exacerbate acute kidney injury (AKI), by degrading Mitofusin-2 (MFN2) leading to mitochondrial fragmentation and impaired bioenergetics." (PMID 41567979, 2025). "The BUN-to-creatinine ratio, which is used to determine the possible cause of acute kidney injury, is also normal in LRRK2-/- mice, suggesting that the renal filtration function is not significantly affected in LRRK2-/- mice up to 12-14 months of age." (PMID 22230652, 2012).
age (2 papers, 2021 to 2024). A temporal measurement of the time period elapsed since an identifiable point in the life cycle of an organism. "LRRK2 mutations are a common cause of age related autosomal-dominant Parkinson’s disease." (PMID 38519892, 2024).
asthma (2 papers, 2019 to 2022). "The typical differential genes concentrated in autophagy-related signaling pathways in MC4 (e.g., BECN1, ATG7 and LRRK2) were found to be downregulated in the asthma group compared with the control group (p < 0.05)." (PMID 36439114, 2022).